CPSF6 (cleavage and polyadenylation specific factor 6)
Diseases named in the same sentence as CPSF6 in open-access papers (continued):
Sharing a sentence is not in itself a finding about the gene and the disease.
infection (continued). "CPSF6 depletion had no additional effect on infection by the A77V variant, indicating that its phenotype is indeed due to loss of CPSF6 binding (bottom panels show data for AAV mediated depletion)." (PMID 30672737, 2019). "Together, these data raised the possibility that the interaction of incoming HIV-1 CA with CPSF6 may help protect infection from MX2-independent IFN-α-induced blocks." (PMID 27279606, 2016). "Meanwhile, neither depletion of CPSF6 nor introduction of CPSF6 non-binding CA mutations N74D or T107A reduces infection of HIV-1 in single round replication assays in cell lines, whilst in macrophages N74D or CPSF6 depletion inhibits replication." (PMID 25356722, 2014). "In this assay, restriction of infection occurs when viral capsids are recognized by CPSF6-358." (PMID 24415937, 2014). "CPSF6 depletion by siRNA rendered cells more permissive to infection by T54A (p<0.002)." (PMID 24415937, 2014). "Consistent with our hypothesis, we observed that 87% of all RTC/PIC were positive for CPSF6 upon infection of the TNPO3 knock-down cell line (87 RTC/PIC analyzed)." (PMID 25517934, 2014). "As T54A is also inhibited for infection of growth-arrested HeLa cells, we hypothesized that endogenous CPSF6 contributes to inhibition of cell cycle-dependent HIV-1 CA mutants." (PMID 24415937, 2014). "Finally, CPSF6 depletion inhibits infection of primary macrophages by revealing HIV-1 to innate immune sensing." (PMID 25356722, 2014). "Moreover, infection by another CsA-dependent mutant T54A is rescued by addition of A105T, which is present in the CA binding site for CPSF6 and confers resistance to CPSF6-358." (PMID 24663101, 2014). "In agreement with previous observations, cytosolic CPSF6 inhibited infection of HIV-2 and SIVmac." (PMID 23622145, 2013). "Because CPSF6 binds the HIV-1 core, we decided to test whether the cytoplasmic CPSF6 (NES-CPSF6) influences the stability of the HIV-1 core during infection." (PMID 23622145, 2013). "Furthermore, we observed that HIV-1 titre was reduced 6.3-fold in cells expressing CPSF6-358, whereas efficient infection was observed in cells expressing CPSF6-FL or CPSF6-358-NLS." (PMID 22956906, 2012). "We found that the infection of human cell lines and primary T cells with wild-type HIV-1 triggered APA changes, whereas APA changes were not induced by infection with HIV-1 bearing N74D or A77V mutation in the capsid protein, which prevents the capsid protein from interacting with CPSF6." (PMID 41405390, 2026). "We also showed that infection by HIV-1 bearing a capsid mutation that prevents the interaction of the viral capsid with CPSF6 was unable to modulate APA, suggesting that the ability of the viral capsid to interact with CPSF6 is essential for modulating cellular APA." (PMID 41405390, 2026). "Furthermore, CPSF6 lacking a nuclear localization signal localizes to the cytoplasm and restricts infection, in some experiments, through causing cytoplasmic uncoating, although inhibition by competing for Sec24C and NPC FG binding also likely has a role." (PMID 39804283, 2025). "However, in T-cells, CPSF6 already displayed punctate staining before infection." (PMID 38793552, 2024). "One of the key questions in the CPSF6 area of investigation is to understand whether the induction of condensates is important for HIV-1 productive infection meaning what will happen to an HIV-1 wild type virus that cannot induce the formation of CPSF6 condensates." (PMID 37414787, 2023). "Similarly, infection by viruses with capsid mutations A77V, N57S, G208R, or A14C/E45C did not trigger the formation of CPSF6 condensates in NS compared to wild type." (PMID 37414787, 2023). "Interestingly, an HIV-1 virus with the cyclosporin A (CsA)-dependent capsid mutant A92E showed decreased formation of CPSF6 condensates, which was rescued by the addition of CsA, and the increase in HIV-1-A92E infection with CsA was proportional to the formation of nuclear CPSF6 condensates." (PMID 37414787, 2023).
infection (continued). "Thus, the CPSF6 condensates induced by wild-type HIV-1 are important for infection." (PMID 37414787, 2023). "Depletion of HIV-1 cofactor CPSF6 does not typically cause a defect in infection in cell lines." (PMID 32553106, 2020). "In addition to CA itself, cellular CA-interacting proteins have been suggested to regulate or otherwise influence HIV-1 nuclear import and infection, including the peptidylprolyl isomerase cyclophilin A (CypA) and the mRNA processing protein cleavage and polyadenylation specificity factor 6 (CPSF6)." (PMID 30084827, 2018). "Thus, CPSF6 appears to specifically inhibit infection by the HIV-1 T54A mutant." (PMID 24415937, 2014). "We depleted endogenous CPSF6 and infected the cells either with CA mutants that become dependent on cell division (E45A, Q63A/Q67A, A92E, G94D, and Q219A) or those that are impaired for infection but maintain cell cycle independence for infection (P38A, E71A, E128A/R132A and R143A)." (PMID 24415937, 2014). "This difference likely reflects the biology of infection, where capsid–CPSF6 interactions modulate CFIm function transiently and only to a partial extent, in contrast to the complete disruption produced by genetic depletion of CPSF6." (PMID 41405390, 2026). "CPSF6, along with NS factors, contains IDRs that can guide HIV-1 to the correct nuclear location for successful infection or allow the virus to remain sequestered during drug treatment, forming reservoirs." (PMID 41493399, 2026). "Our goal was to capture the fusion event between the HIV-induced CPSF6 puncta and NS, providing insights into the dynamics of how HIV manipulates host nuclear structures during infection." (PMID 41493399, 2026). "HIV-1 viral core transport to the nucleus, an early infection event, triggers the redistribution of cleavage and polyadenylation specificity factors (CPSF) 5 and CPSF6 to nuclear speckles, forming puncta-like structures." (PMID 41405390, 2026). "To probe how the effects of CPSF6 on PIC function influenced HIV-1 infectivity, we carried out single-round infection studies in both CKO and CKI cells." (PMID 40202316, 2025). "Following infection with HIV-1, we observed differences in reporter gene expression amongst the nuclear-rescued CPSF6–358 constructs." (PMID 38979149, 2024). "After infection with VSV-eGFP, or treatment with Poly (I:C) or Poly (dA:dT), Cpsf6-/- L929 cells also exhibited higher expression of IFNB and ISGs, but this increase was suppressed in Cpsf6-/- L929CPSF6 cells." (PMID 38416782, 2024). "Unintegrated HIV DNA colocalized with CPSF6 and HIV capsid (CA, p24) was found in the cytoplasm and nuclear periphery at days 1 and 3 post infection." (PMID 38669184, 2024). "We also observed differential sensitivities to the CPSF6-NLS chimeras amongst related lentiviruses, as infection with HIV-2 and SIVmac highlighted further virus-specific phenotypes." (PMID 38979149, 2024). "To better understand the role of CPSF6’s NLS, we attached heterologous NLSs to CPSF6–358 to determine the impact of divergent NLSs on nuclear import and infection by HIV-1 and related lentiviruses." (PMID 38979149, 2024). "The average number of CPSF6 puncta per cell was 2–3 for low MOI infections and 2–4 puncta/cell for infections with 40 times more virus." (PMID 38793552, 2024). "Overall, our work demonstrated that CPSF6 and CPSF5 are forming biomolecular condensates that are important for infection of wild type HIV-1 viruses." (PMID 37414787, 2023). "Whereas CsA treatment, predictably, does little to affect P90A infection in the POM121 or Nup153 knockdown cells, CPSF6 depletion potently enhances infection when in conjunction with either knockdown." (PMID 37355754, 2023). "As a proof of principle, we infected A549 cells by an HIV-1 virus expressing luciferase as a reporter of infection (HIV-1-Luc) at an MOI = ~ 1–2 and showed that infection triggers the translocation of CPSF6 to NS." (PMID 37414787, 2023).
infection (continued). "CA also provides binding interfaces for host factors like cyclophilin A (CypA) and cleavage and polyadenylation-specific factor 6 (CPSF6) to promote infection." (PMID 35719891, 2022). "First, the 5Mut virus lost the ability to interact with CPSF6 and CypA and became less dependent on NUP153 and NUP358 for infection." (PMID 34702294, 2021). "Accordingly, truncation of the C terminus of CPSF6 leads to increased cytoplasmic expression and inhibition of HIV-1 nuclear entry and infection in a TNPO3-dependent manner." (PMID 33758083, 2021). "The interaction between HIV-1 CA and CPSF6 impedes interferon (IFN)-mediated innate responses, allowing HIV-1 to escape from immune sensing and favouring infection." (PMID 31465518, 2019). "We have analyzed nuclear entry of HIV-1 and productive infection in post-mitotic human MDM with a focus on the viral CA and the cellular CPSF6 protein." (PMID 30672737, 2019). "Because of the similar phenotypes observed for HIV-1-GFP infection when using BI-2 and PF74, we tested the ability CPSF6 to bind in vitro assembled HIV-1 CA-NC complexes in the presence of BI-2." (PMID 25496772, 2014). "To further understand the role of CPSF6 in the inhibition of HIV-1 observed in TNPO3-depleted cells, we measured the levels of 2-LTR circles during infection of TNPO3 K.D. cells." (PMID 23622145, 2013). "Subsequently, we infected these cells with HIV-1 and analysed the presence or absence of CPSF6 puncta at 24 hr post-infection." (PMID 41493399, 2026). "We have also identified HIV-induced CPSF6 puncta formation independent of NS at early stages post-infection, with a progressive increase in CPSF6 puncta colocalizing with NS over time." (PMID 41493399, 2026). "The interaction between HIV-1 and the cellular protein CPSF6 has been known for over 15 years; however, depletion of CPSF6 does not impair productive infection." (PMID 41405390, 2026). "Taken together, these data are consistent with a model in which CPSF6 recruitment and relocalization by incoming capsid cores can trigger transcriptional reprogramming of infected cells through changes in APA to enhance permissivity to infection." (PMID 41385587, 2025). "This is dependent on the interaction with the core as infection with the N74D capsid mutant, which does not bind CPSF6, does not lead to CPSF6 relocalization to nuclear speckles." (PMID 41385587, 2025). "CPSF6 binds to the HIV-1 capsid and plays multiple roles during the early steps of infection." (PMID 40202316, 2025). "In contrast, the SV40, HNRNP K, and HNRNP A1 NLSs rescued infection to levels that were indistinguishable from CPSF6-FL." (PMID 38979149, 2024). "As expected, when 100% of the gag-pol contained the A77V CA substitution, the VLPs produced did not induce any CPSF6 puncta upon infection." (PMID 38793552, 2024). "At day 5 post-challenge, CPSF6 knock-out cells showed a 4- to 6-fold increase in infection relative to the non-targeting controls." (PMID 39678349, 2024). "Nevertheless, these data are consistent with a model in which CPSF6 recruitment and relocalization by incoming capsid cores triggers transcriptional reprogramming of infected cells through APA to enhance permissivity to infection." (PMID 39678349, 2024). "To determine if chimeric CPSF6-NLS constructs impair HIV-1 intranuclear trafficking to NSs, we utilized GIR virus in combination with an SC35 stain to visualize colocalization with NSs at 8 h post-infection." (PMID 38979149, 2024). "Likewise, the 3’ UTRs of Ddx58, Ddx3x, Ddx21, Ifit2 and Ifit3, were significantly shorter in primary BMDMs from Cpsf6+/- mice, and such shortening was more pronounced upon VSV-eGFP infection." (PMID 38416782, 2024). "Knock-out of IFNAR1 resulted in a roughly two-fold increase in infection over the non-targeting control compared to the 4- to 5-fold increase observed in the CPSF6 knock-out cells." (PMID 39678349, 2024).
infection (continued). "This suggests that CPSF6 knock-out lowers a surmountable barrier to infection as opposed to facilitating a rate-limiting step that cannot be overcome by mass action." (PMID 39678349, 2024). "CPSF6-NP NLS and MX2 NLS constructs in T cells and macrophages behaved largely similarly as they did in HeLa cells, with the exception that the CPSF6-NP NLS chimera supported comparatively less infection of THP-1 cells." (PMID 38979149, 2024). "Widefield deconvolution fluorescent microscopy imaging confirmed that infection with viruses with WT capsid led to formation of CPSF6 puncta in cell nuclei, and these puncta were not present in the mock or N74D infected cells." (PMID 39678349, 2024). "A similar result was seen in MDMs, although the overall number of cells with CPSF6 foci was lower as the infection was likely lower in MDMs, and all cells were counted, not just CA-positive cells." (PMID 38793552, 2024). "Next, we determined that inhibition of viral integration by infection with HIV-1-D116N, which is a virus that has the integrase mutation D116N15, did not alter the formation of CPSF6 condensates in NS." (PMID 37414787, 2023). "While N57A and K70A HIV-1 were less sensitive to Nup35 depletion, Q63A/Q67A and T107A HIV-1 resembled WT HIV-1 in infection indicating that CPSF6-interaction on its own does not predict Nup35 dependence." (PMID 37355754, 2023). "Remarkably, preventing the formation of CPSF6 condensates inhibits the infection of wild type HIV-1 but not of HIV-1 viruses bearing the capsid changes N74D and A77V, which do not form CPSF6 condensates during infection." (PMID 37414787, 2023). "To further explore the role of these condensates in infection, we used immunofluorescence microscopy to screen several human cell lines infected with HIV-1-GFP at a multiplicity of infection (MOI) 1–2 (infecting > 90% of HT1080 cells) for CPSF6 condensates." (PMID 37414787, 2023). "We have analyzed the roles of LEDGF/p75 and CPSF6 in primate and non-primate lentiviral integration targeting at the chromosome level using knockout cells or from infections initiated with CA mutant viruses." (PMID 35203306, 2022). "Sec24c is nearly identical to CPSF6 in its requirement for infection by diverse lentiviruses, as EIAV and FIV were not affected by Sec24c knockout in contrast to some SIV strains of which infectivity were reduced in cells lacking Sec24c." (PMID 34702294, 2021). "In contrast, CPSF6 complex formation was indistinguishable from background after infection with N74D HIV-1." (PMID 33758083, 2021). "Although high-speed imaging of HIV-1 particles in CD4+ T cells was not possible, infection results after CPSF6 depletion and/or CsA treatment in primary PBMC largely mimicked those seen in HeLa cells." (PMID 33758083, 2021). "Crucially, infection with the hyper-stable mutants did not promote CPSF6 re-localisation to nuclear speckles, despite the mutant capsids being competent for CPSF6 binding." (PMID 34543344, 2021). "Upon infection, CPSF6 formed clusters that co-localized with CA, vDNA, and IN-eGFP spots in the cell nucleus, while no CPSF6 was detected in cytoplasmic viral complexes." (PMID 33573241, 2021). "While infection by BIV was similarly unaffected, CPSF6-358 mildly restricted EIAV." (PMID 32994325, 2020). "In the absence of CPSF6, the MxB block to infection was accompanied by a reduction in 2LTR circles, as in wild type cells, suggesting MxB mediated suppression of nuclear entry was retained." (PMID 32553106, 2020). "As reported, HIV-1 GFP R9 bearing CA mutant N74D, which does not bind the cellular cofactor CPSF6, was insensitive to MxB and MxB induction did not strongly suppress infection, viral DNA synthesis, or 2LTR circle formation." (PMID 32553106, 2020). "Relocalization of CPSF6 to the cytosol could decrease its availability to bind to HIV-1 CA and contribute to the increased resistance to infection observed in LGMD1F patients." (PMID 31465518, 2019).
infection (continued). "Although CPSF6 depletion does not significantly affect HIV-1WT infection in vitro, selective pressure appears to maintain CPSF6-CA interactions in vivo." (PMID 30084827, 2018). "Curiously, the effects of CPSF6 depletion were reminiscent of the effects of NUP155 depletion, in that they similarly reduced the respective CsA-induced enhancement or inhibition of HIV-1WT, HIV-1A92E, and HIV-1N57S infection." (PMID 30084827, 2018). "In contrast, genetic disruption of CPSF6 did not increase the sensitivity of wild-type or CA mutant HIV-1 to IFN-α-induced effectors in THP-1 cells, arguing that CPSF6 does not play a role in protecting infection from IFN-α-induced blocks." (PMID 27279606, 2016). "In contrast, infection by none of the cell cycle-independent CA mutants was affected by CPSF6 depletion." (PMID 24415937, 2014). "In this study, we showed that depletion of endogenous CPSF6 rescues infection by HIV-1 CA mutants that are impaired for infection of non-dividing cells." (PMID 24415937, 2014). "We observed that infection by CA mutants restricted by CPSF6 is less dependent or independent of the nucleoporins RanBP2 and Nup153." (PMID 24415937, 2014). "Interestingly, we found a parallel between the ability of BI-2 to inhibit infection by HIV-GFP and SIVmac-GFP with the ability of BI-2 to prevent the binding of CPSF6 with the HIV-1 and SIVmac cores." (PMID 25496772, 2014). "These control experiments revealed that simultaneous depletion of TNPO3 and CPSF6 does not affect HIV-1-N74D infection." (PMID 23622145, 2013). "To test our hypothesis that CPSF6 interacts directly with the HIV-1 CA we used a combination of biophysical, structural and cellular infection approaches." (PMID 22956906, 2012). "However, we observed no significant impact of CPSF6 knock-out on infection with the CCR5-tropic JR-FL strain." (PMID 41385587, 2025). "To determine if CPSF6 knock-out could be altering the innate immune response to infection, we assessed expression of a representative ISG, MX1, in primary CD4+ T cells from the four independent donors above at 5 days post-infection." (PMID 39678349, 2024). "Overall, we demonstrate that the expression dynamics of CPSF6 and its effect on APA processing can fine-tune the host immune responses, a finding that may have implications for developing new therapeutic strategies against pathogen infections or cancers." (PMID 38416782, 2024). "The observation that 2-LTR circle formation was similar in cells with nuclear localized CPSF6 fusions suggests that the fusion constructs do not negatively impact core uncoating during infection, as 2-LTR circle formation requires the non-homologous end joining machinery." (PMID 38979149, 2024). "Because inhibition of reverse transcription did not affect the formation of CPSF6 condensates, we determined whether infection by viruses without a genome triggered the recruitment of CPSF6 to NS." (PMID 37414787, 2023). "The contribution of HIV-1-induced CPSF6 condensates to infection is not understood." (PMID 37414787, 2023). "However, CPSF6 depletion led to a significant decrease in spreading infection with WT HIV-1 but not with N74D HIV-1 in MDM." (PMID 33758083, 2021). "However, there was no such redistribution of CPSF6 during infection with any of the hyper-stable mutants which showed similar CPSF6 staining to uninfected cells." (PMID 34543344, 2021). "However, infection with WT HIV-1 failed to induce higher-order CPSF6 complex formation in the cytoplasm (data not shown), consistent with previous results and indicative of less cytoplasmic CPSF6 expression in MDM than in HeLa cells." (PMID 33758083, 2021). "Infection profiles of GFP-expressing lentiviruses versus MLV were initially assessed on wild-type (WT) HEK293T cells as well as isogenic derivatives that were knocked out for LEDGF/p75 (LKO for LEDGF knockout), CPSF6 (CKO), or both factors (DKO for double knockout)." (PMID 32994325, 2020).